LRRK2 (leucine rich repeat kinase 2)
Diseases named in the same sentence as LRRK2 in open-access papers (continued):
Sharing a sentence is not in itself a finding about the gene and the disease.
Parkinson disease (continued). "In addition to successful differentiation of control iPSC lines into iMGL, the 2.9 protocol was also confirmed to allow the differentiation of Parkinson’s disease patient-derived lines harboring glucocerebrosidase (GBA) or leucine-rich repeat kinase 2 (LRRK2) pathogenic variants." (PMID 38576039, 2024). "However, LRRK2 is a well-known gene associated with Parkinson’s disease." (PMID 36562724, 2023). "The identification of this pathway for LRRK2-dependent suppression of the degradative activity of lysosomes opens up opportunities to define more detailed molecular mechanisms and to determine the contributions of such regulation to both normal cell biology and to Parkinson’s disease risk." (PMID 37487100, 2023). "Moreover, different variants of LRRK2 are linked to CD and Parkinson’s disease." (PMID 37443813, 2023). "Variants in the GBA1 and LRRK2 genes are the most common genetic risk factors associated with Parkinson disease (PD)." (PMID 36034282, 2022). "LRRK2 gene rate variants in haplotype might be a potential risk factor for endemic parkinsonism." (PMID 35054514, 2022). "LRRK2 phosphorylated Rab8A and Rab10, in complex with RILPL1, inhibit the formation of primary cilia that are implicated in controlling a Sonic hedgehog-driven neuroprotective pathway that could provide a mechanism by which LRRK2 is linked to Parkinson's disease." (PMID 33459343, 2021). "Mutations in leucine-rich repeat kinase 2 (LRRK2) cause autosomal dominant Parkinson disease (PD), while polymorphic LRRK2 variants are associated with sporadic PD." (PMID 34914695, 2021). "This latter observation is of particular significance, as it implies that the physiological function of LRRK2 may contribute to the disease process in Parkinson's, although the functional consequences of the non-coding variants at the LRRK2 locus are as yet poorly understood." (PMID 34328508, 2021). "Our results identify a physiological role for LRRK2 in the regulation of basal mitophagy in vivo and underline the potential value of pharmacological inhibition of LRRK2 as a potential therapeutic strategy to ameliorate aspects of Parkinson’s disease driven by mitochondrial dysfunction." (PMID 34340748, 2021). "In a study of dominant mutation of LRRK2 (leucine-rich repeat kinase 2) in a Parkinson’s disease (PD) model, TAOK3, serine/threonine kinase 3 (STK3), STK24, and STK25 were identified to be novel LRRK2 substrates that may be involved in LRRK2-induced synaptic dysfunction and neurite fragmentation." (PMID 33050415, 2020). "This study is performed to determine whether LRRK2, a complex kinase that had been originally been identified as the causative molecule of familial and sporadic Parkinson’s disease, plays important roles in cytokine production and antigen-presenting ability in BMDCs." (PMID 32164260, 2020). "Since 2005, The Michael J. Fox Foundation for Parkinson’s Research (MJFF) has invested significant funding and non-funding effort to accelerate research and drug development activity around the Parkinson disease (PD)-associated protein LRRK2." (PMID 32796584, 2020). "The age of onset of autosomal-dominant Parkinson disease (PD), caused by LRRK2, is approximately 53 years, while autism was observed in DGDP289A at age two." (PMID 31963867, 2020). "Although the cause of most Parkinson’s disease remains unknown, autosomal dominant mutations in the leucine rich repeat kinase 2 (LRRK2) gene account for 1–2% of all cases (and 18% of cases in those of Ashkenazi Jewish descent) and lead to activation of the LRRK2 kinase." (PMID 30398148, 2018). "Also included in the list are transcripts related to dopamine synthesis and signaling such as tyrosine hydroxylase and dopamine receptor D2 as well as transcripts that associate to Parkinson's disease following genetic mutation (i.e., alpha-synuclein, Park2, and Lrrk2)." (PMID 30740124, 2018).
Parkinson disease (continued). "Indeed different forms of parkinsonism with a shared molecular background have been identified, e.g., mutations in the LRRK2 gene were described as causing typical PD, MSA or PSP with histopathological features ranging from synucleinopathies up to tau aggregation." (PMID 30420802, 2018). "Interestingly, the G2019S LRRK2 mutation is also found in 1–2% of sporadic Parkinson's cases." (PMID 29127255, 2018). "Moreover, patients with VPS35[D620N] associated Parkinson's might benefit from LRRK2 inhibitor treatment that have entered clinical trials in humans." (PMID 29743203, 2018). "There is reasonable hope that this may be different in LRRK2 associated Parkinson's." (PMID 29127255, 2018). "In addition, a prior study suggested that a LRRK2 polymorphism (p.Q1111H) specific to Latino and Amerindian populations might be a risk factor for Parkinson’s disease, but this finding requires replication." (PMID 28649619, 2017). "Genetic variation in the leucine-rich repeat kinase 2 (LRRK2) gene associates with Parkinson disease (PD) susceptibility." (PMID 29166931, 2017). "It will also be important to explore whether elevated Rab protein phosphorylation can be observed in Parkinson's disease patients who are carriers of LRRK2 mutations and whether a subgroup of Parkinson's disease patients with idiopathic disease also display elevated Rab phosphorylation." (PMID 27474410, 2016). "Moreover, LRRK2 participates in canonical Wnt signaling as a scaffold, and it has been proposed that decreased LRRK2-mediated Wnt signaling underlies the neurodegeneration observed in Parkinson’s disease." (PMID 27504085, 2016). "Therefore, LRRK2 mutations could disrupt normal Ca2+ signaling as an early cellular event in the development of Parkinson’s disease." (PMID 27242426, 2016). "The LRRK2 G2019S mutation is found at higher frequency among Parkinson disease (PD) patients of Ashkenazi Jewish (AJ) ancestry." (PMID 26436106, 2015). "Importantly, it has been reported that LRRK2 harboring familial Parkinson mutations exhibits reduced cellular phosphorylation by an unknown mechanism, implicating the disturbed cellular phosphorylation in the toxic mechanism of familial Parkinson mutant LRRK2." (PMID 24836358, 2014). "However, as we outline below, decreased canonical Wnt signaling associated with familial PARK8 mutations suggests that transgenic LRRK2 animal models of Parkinson’s disease might present with discrete developmental phenotypes associated with Wnt dysfunction." (PMID 23754980, 2013). "Furthermore, LRRK2 mutations account for up to 2% of sporadic Parkinsonism." (PMID 24244710, 2013). "While the etiology of the disease remains largely unknown, with the majority of cases appearing to be sporadic, genetic evidence has linked several genes to an increased risk of an individual developing Parkinson’s, including the leucine-rich repeat kinase 2 (LRRK2) gene." (PMID 23799078, 2013). "With this background, we screened 150 familial PD cases from our UK familial Parkinson's Disease series, in which we have previously identified LRRK2, VPS35 and SNCA mutations in order to determine whether we could provide further that this gene is indeed a PD-related locus." (PMID 22561553, 2012). "Parkinson's disease-linked LRRK2 mutations that associated with enhanced kinase activity may affect retinoic acid receptor signaling during neurodevelopment and/or neuronal maintenance as has been shown in other mouse models of chronic neurodegenerative diseases." (PMID 21695257, 2011). "Variants in the LRRK2 and GBA1 genes are among the most common risk factors associated with Parkinson's disease (PD)." (PMID 41786767, 2026). "Eight loci-PRKN, SNCA, GBA1, LRRK2, APOE, MTHFR, SYT11, and NR4A2-emerged as recurrently associated with Parkinson's disease." (PMID 41798285, 2026). "Leucine-rich repeat kinase 2 (LRRK2) is a multidomain serine/threonine kinase and a major genetic contributor to Parkinson's disease (PD)." (PMID 42072709, 2026).
Parkinson disease (continued). "In summary, the exploration of specific genetic mutations, such as those in LRRK2 and PINK1, provides valuable insights into the intricate landscape of Inherited Parkinson’s Disease." (PMID 40291849, 2025). "In the context of neurodegenerative diseases such as Parkinson’s disease, the effects of homotaurine were assessed in 3D neural epithelial stem cell (NESC) organoids derived from iPSCs carrying the LRRK2-G2019S mutation." (PMID 40227236, 2025). "This information will be valuable for developing new therapeutic approaches targeting LRRK2 and Parkinson's disease." (PMID 41192797, 2025). "In studies on Parkinson’s disease, Drosophila LRRK2 models largely confirm, validate, or sometimes anticipate, the findings arising from higher eukaryote experimental models." (PMID 40076730, 2025). "Leucine-rich repeat kinase 2 (LRRK2) phosphorylates a subset of Rab GTPases that regulate receptor trafficking; activating mutations in LRRK2 are linked to Parkinson’s disease." (PMID 40166354, 2025). "Within the RAB protein family, RAB32 has also been implicated in late-onset Parkinson’s disease, showing reduced penetrance; notably, RAB32 is phosphorylated by LRRK2." (PMID 41179085, 2025). "Leucine-rich repeat kinase 2 (LRRK2) is an essential regulator in cellular signaling and a major contributor to Parkinson’s disease (PD) pathogenesis." (PMID 40764514, 2025). "LRRK2 has been found to be a substrate for ERAD which hints towards the role of ER stress in LRRK2 parkinsonism." (PMID 40332013, 2025). "In conclusion, LRRK2 plays a pivotal role in the pathological processes of neuroinflammation and ferroptosis in Parkinson’s disease." (PMID 40169487, 2025). "This is contrary to the present literature that shows that p-RAB10 is instead positively correlated with LRRK2 parkinsonism." (PMID 40332013, 2025). "Playing a crucial role in the progression of Parkinson’s disease, leucine-rich repeat kinase 2 (LRRK2) has gained great prominence as a potential drug target." (PMID 40802138, 2025). "A mutation in the leucine-rich repeat kinase 2 (LRRK2) gene, also known as PARK8, is the most common genetic cause of Parkinson’s disease." (PMID 40650193, 2025). "LRRK2, extensively studied in the context of Parkinson's disease is functionally impaired in other pathological conditions as well, including inflammatory bowel disease, cancer, and cardiovascular diseases." (PMID 40907896, 2025). "In the double-blind randomized clinical phase I trial (NCT04056689) conducted by Denali Therapeutics, DNL151, an LRRK2 inhibitor, showed a fairly clear therapeutic benefit on Parkinson’s disease." (PMID 40650193, 2025). "Our findings of increased Rab12 phosphorylation and pS106-Rab12 labeling of GVBs and pathology across synucleinopathies and tauopathies suggest that LRRK2 plays a role in other neurodegenerative diseases in addition to Parkinsonism." (PMID 40661559, 2025). "Defining these mechanisms is essential for explaining how inappropriate LRRK2 activation contributes to Parkinson’s disease as well as for understanding physiological functions of LRRK2." (PMID 41332754, 2025). "Candidates for engaging these pathways in the context of Parkinson’s disease pathogenesis include risk genes such as Rab32 and VPS35 that are known to activate LRRK2 and VPS13C that promotes the repair of damaged lysosomes." (PMID 41332754, 2025). "The importance of LRRK2 kinase activity for Parkinson’s disease is well supported by the genetics of both sporadic and familial forms of the disease." (PMID 39812709, 2025). "In Parkinson’s disease, it decreases α-synuclein aggregation by targeting the SNCA gene and restores mitochondrial function by correcting mutations in LRRK2 and PINK1." (PMID 40255230, 2025). "The identification of CASM as a convergence point for multiple stimuli that activate LRRK2 provides a foundation for further investigation of how lysosome dysfunction contributes to Parkinson’s disease." (PMID 39812709, 2025).
Parkinson disease (continued). "Inhibition of LRRK2 reverses these effects, restoring both GCase function and lysosomal degradation, and reducing α-synuclein accumulation in models of Parkinson’s disease." (PMID 40523620, 2025). "In neurodegenerative diseases, notably, frontotemporal dementia (FTD) and Parkinson’s disease (PD), genetic mutations—including MAPT, LRRK2, PINK1, PRKN, and SNCA—have been reported to alter Nrf2 signaling, both in vitro and in vivo." (PMID 41154499, 2025). "In individuals with Parkinson’s, where abnormal folding and aggregation of α-Syn are typically observed, Lrrk2 overactivation is often found." (PMID 41282615, 2025). "LRRK2 (leucine-rich repeat kinase-2) is a multi-domain protein that is encoded by a gene subject to polymorphisms and/or mutations linked to IBD, Parkinson’s disease, and leprosy." (PMID 41246319, 2025). "RAB32’s role in regulating LRRK2-mediated late endosomal trafficking relates to Parkinson’s disease pathogenesis." (PMID 41256702, 2025). "DNL151 (BIIB122), a LRRK2 degrader developed by Denali and Biogen, is currently in Phase 2 clinical trials for Parkinson’s disease." (PMID 40574056, 2025). "Pathogenic variants in the LRRK2 gene are one of the most commonly identifiable monogenic causes of Parkinson ́s disease (PD, PARK-LRRK2)." (PMID 39962078, 2025). "Although another Parkinson’s disease protein, LRRK2, is also recruited to stressed or damaged lysosomes, its recruitment occurs at much later stages and by different mechanisms." (PMID 40211074, 2025). "In conclusion, this study evidence that LRRK2 plays a central role in the pathogenesis of Parkinson’s disease by orchestrating microglial neuroinflammation and ferroptosis through the p62-Keap1-Nrf2 signaling cascade." (PMID 40169487, 2025). "Aberrant DNA methylation has been observed in genes linked to neurodegeneration, including APP, PSEN1, and TREM2 in Alzheimer’s disease (AD), as well as SNCA and LRRK2 in Parkinson’s disease (PD)." (PMID 40076852, 2025). "Overexpression of pathological mutants of LRRK2 that render the kinase hyperactive accounts for 2% of all Parkinson’s cases and up to 20% of the cases in North African Berbers and Ashkenazi Jews." (PMID 40801573, 2025). "Leucine-rich repeat kinase 2 (LRRK2) is an important protein in Parkinson’s disease development, and multiple pieces of evidence point out the role of this protein in several steps of autophagy." (PMID 38534317, 2024). "In contrast, fibroblasts with Parkinson’s mutations in PINK1 and LRRK2 demonstrated a significant increase in ΔΨm after 24 h of incubation (N = 5 experiments for PINK1, N = 4 experiments for LRRK2)." (PMID 38429623, 2024). "Comparison of Parkinson’s disease (PD) mutants in the HPLC-based GTPase assay for the LRRK2 full-length protein." (PMID 39699947, 2024). "Genetic mutations and protein abnormalities linked to diseases like Alzheimer’s (APP, PSEN1, PSEN2), Parkinson’s (PINK1, LRRK2), and Huntington’s (HTT) can be detected in fibroblasts, reflecting similar changes in brain pathology." (PMID 39766775, 2024). "In this proof-of concept study we evaluate the potential of extracellular miRNA signatures to identify LRRK2-driven molecular patterns in Parkinson’s disease." (PMID 38848197, 2024). "There are a number of genes that are found in both aspects of genetic risk for Parkinson's disease—SNCA but also LRRK2 on chromosome 12 and GBA1 on chromosome 1." (PMID 38368938, 2024). "The overexpression or mutation of key genes linked to Parkinson’s disease progression, such as SCAN and LRRK2, has been identified." (PMID 38542121, 2024). "Our study provides significant insights into the neuroprotective role of miR-71 in C. elegans in the context of LRRK2-induced Parkinson’s disease." (PMID 39201481, 2024).
Parkinson disease (continued). "Studies on human-induced pluripotent stem cells (iPSC) and an iPSC-derived neuronal model for familial and sporadic Parkinson’s disease demonstrated a direct interaction between Miro-1 and another Parkinson protein, Leucine-rich repeat kinase 2 (LRRK2)." (PMID 38607086, 2024). "Leucine-rich repeat kinase 2 (LRRK2) and α-synuclein are involved in the pathogenesis of Parkinson’s disease." (PMID 39483283, 2024). "Prodromal gut inflammation exacerbates Parkinson’s disease endophenotypes in mouse carriers of human LRRK2 G2019S in a sex-dependent manner, showing increased α-synuclein positive macrophages in the colon and brain microglia." (PMID 38750146, 2024). "The development of inhibitors targeting LRRK2 for the treatment of Parkinson’s disease has already garnered significant attention." (PMID 39770531, 2024). "Leucine-rich repeat kinase 2 (LRRK2), a Rab kinase associated with Parkinson’s disease and several inflammatory diseases, has been shown to localize to stressed lysosomes and get activated to regulate lysosomal homeostasis." (PMID 38227290, 2024). "For Parkinson’s disease, typical examples include α-synuclein, uric acid levels, mutations in relevant genes such as LRRK2 or GBA, and brain MRI, which have been widely applied in Parkinson’s disease risk assessment and symptom diagnosis." (PMID 39066031, 2024). "On the other hand, dopamine receptors are targets to modulate grooming actions in rats, and the stimulation of this dopamine receptor mediates the neuroprotection in a G2019S Lrrk2 genetic model of Parkinson’s disease." (PMID 38256111, 2024). "We also know that treatments for Parkinson’s disease specifically targeting LRRK2 are currently being developed." (PMID 38848197, 2024). "As LRRK2 kinase inhibitors are being trialled as a disease-modifying therapy in Parkinson's disease, further work is needed to establish their potential in RAB32 Ser71Arg Parkinson's disease." (PMID 38614108, 2024). "Parkinson ́s disease (PD) is a common neurodegenerative movement disorder and leucine-rich repeat kinase 2 (LRRK2) is a promising therapeutic target for disease intervention." (PMID 38191886, 2024). "Leucine-rich repeat kinase 2 (LRRK2) encodes a kinase that is involved in vesicular membrane trafficking and is one the genes mutated in familial cases of Parkinson’s disease." (PMID 38523660, 2024). "LRRK2, a major modulator of neuroinflammation involved in the pathogenesis of Parkinson’s disease, is upregulated in both depressive (logFC = 0.56) and VDD (logFC = 2.57) patients." (PMID 38256187, 2024). "Our findings suggest the need to investigate concurrent immune and inflammatory diseases in Parkinson’s disease, and especially in LRRK2 PD." (PMID 39175765, 2024). "PKC activators were originally considered for Alzheimer's disease and nanobodies that act as allosteric activators of leucine-rich repeat kinase 2 (LRRK2) have been discussed in the context of Parkinson's disease." (PMID 39502833, 2024). "Twenty years ago, the leucine-rich repeat kinase 2 (LRRK2) gene was identified as a key driver of Parkinson’s disease (PD) pathophysiology." (PMID 38854119, 2024). "In conclusion, our study highlights the potential of miR-71 as a key player in neuroprotection against LRRK2-induced neurodegeneration in a C. elegans model of Parkinson’s disease." (PMID 39201481, 2024). "Among the genetic factors classified in Autosomal dominant forms that influence Parkinson’s disease are LRRK2, SNCA, VPS35, and GBA." (PMID 39770531, 2024). "The involvement of LRRK2 in Parkinson’s disease appears to have significant differences between men and women." (PMID 38933683, 2024). "LRRK2 is a pivotal factor not only in Parkinson’s disease but also in the pathogenesis of dementia with Lewy bodies." (PMID 38765669, 2024).